PIK3CA (phosphatidylinositol-4,5-bisphosphate 3-kinase catalytic subunit alpha)
Diseases named in the same sentence as PIK3CA in open-access papers (continued):
Sharing a sentence is not in itself a finding about the gene and the disease.
breast cancer (continued). "Previously, alpha isoform-specific PI3K inhibitors were shown to potentiate HER2-targeted therapy in breast cancer cells carrying PI3K pathway alterations with less potent effects on PTEN-loss than PIK3CA-mutant cells." (PMID 39920872, 2025). "Registered clinical trials are evaluating the use of pictilisib in combination with fulvestrant in patients with advanced breast cancer whose tumors harbor a PIK3CA mutation." (PMID 41157256, 2025). "In this study, the authors identified a 41% PIK3CA mutation rate among Chinese breast cancer patients, with exon 20 mutations predominating (62.1%)." (PMID 40472482, 2025). "This review analyzed the impact of PIK3CA mutations on breast cancer, a disease that has long affected women worldwide." (PMID 40142329, 2025). "Among the allosteric inhibitors, MK-2206 has been evaluated as monotherapy in the phase II trial NCT01277757 in patients with advanced breast cancer and tumors harboring PIK3CA or Akt mutations and/or PTEN loss or mutations." (PMID 40647529, 2025). "PIK3CA gene mutations are one of the most common oncogenic mutations in breast cancer, accounting for approximately 30% of all breast cancer cases." (PMID 41280894, 2025). "The effects of acquired PIK3CB mutations in response to PIK3CA inhibition was studied in breast cancer cells after treatment with pictilisib." (PMID 40564038, 2025). "Targeting phosphatidylinositol-4,5-bisphosphate 3-kinase catalytic subunit alpha (PIK3CA) mutations with alpelisib in breast cancer and mutations of the tumour suppressor PTEN are typical examples." (PMID 41463281, 2025). "The aim of the current study was to analyze the frequency, spectrum, and clinical associations of PIK3CA lesions in Russian patients with HR+/HER2− breast cancer." (PMID 40507317, 2025). "This medication targets breast cancer cells with the PIK3CA gene mutation, inhibiting the PI3Kα and Akt-signaling pathway and subsequent tumor growth." (PMID 40136358, 2025). "Activating mutations in PIK3CA are found in up to 70% of proliferative benign lesions and in 35.7% of breast cancers." (PMID 40243654, 2025). "Inhibitors of PI3Kα, most notably alpelisib, have transformed the management of hormone receptor–positive, HER2-negative, PIK3CA-mutated advanced breast cancer, but their use is frequently limited by treatment-emergent hyperglycemia." (PMID 41425618, 2025). "This review synthesizes preclinical and clinical evidence on the mechanistic optimization of inavolisib combined with CDK4/6 inhibitors for PIK3CA-mutated breast cancer." (PMID 41280894, 2025). "Association between PIK3CA mutation status and disease progression in the metastatic breast cancer patients (n = 54)." (PMID 41415546, 2025). "Alpelisib is primarily recognized as an effective treatment for patients with HR+/HER2- breast cancer who harbor PIK3CA mutations." (PMID 41347072, 2025). "While PIK3CA mutations are implicated in breast cancer progression, their prognostic utility requires validation through larger multicenter studies." (PMID 40472482, 2025). "A prior study revealed that PIK3CA mutations correlate with reduced pCR rates in HER2‐positive breast cancer patients receiving neoadjuvant anti‐HER2 therapy." (PMID 39712455, 2025). "Alpelisib is an oral PIK3 inhibitor originally developed for the treatment of PIK3CA-mutated breast cancer." (PMID 40353106, 2025). "SCRIB-associated tumor promotion is related to the PIK3CA (phosphatidylinositol-4,5-bisphosphate 3-kinase catalytic subunit alpha) pathway such as aPKC that is activated in 80% of 110 breast cancer patients particularly in invasive tumors." (PMID 40057606, 2025). "The DFS of breast cancer patients with PIK3CA exon 20 mutation, exon 9 mutation and wild-type were 22.5-months, 32-months and 24-months, respectively." (PMID 40472482, 2025).
breast cancer (continued). "Within various breast cancer subtypes, the distribution of PIK3CA mutations shows slight variability, peaking at 49.5% in luminal A subtypes and dropping to 16.1% in basal‐like breast cancer." (PMID 40206206, 2025). "Our study highlights liquid biopsy as a preferred approach for monitoring ESR1 mutations in breast cancer patients by showing cases where NGS analysis suggests complex tumor heterogeneity with multiple ESR1 as well as PIK3CA mutations at different VAFs." (PMID 40282442, 2025). "A notable example is the p.H1047R hotspot mutation in the PIK3CA gene, which is well-known in human breast cancer and has also been found in canine mammary cancer." (PMID 40446009, 2025). "It was observed that oncogenic mutation in PI3K is directly associated with either activating subsequent mutations in PIK3CA or Akt1 or is linked with decreased expression of PTEN thereby further complicating breast cancer." (PMID 40176859, 2025). "PIK3CA and Akt1 gene mutations are frequently observed in breast cancer, with PIK3CA mutations primarily being detected in HER2+ve and ER+ve breast cancer." (PMID 39858015, 2025). "In particular, East Asian breast cancers have been reported to exhibit distinct mutational patterns, including a higher prevalence of PIK3CA mutations and a lower frequency of GATA3 mutations." (PMID 41008925, 2025). "Multiple studies have shown that PIK3CA is implicated in the pathogenesis and progression of breast cancer." (PMID 41357233, 2025). "Currently, PI3Kα inhibitors, including inavolisib and alpelisib, have demonstrated the capacity to induce durable disease control in patients with PIK3CA‐mutated breast cancer." (PMID 41357671, 2025). "One major direction is broadening the mutation profiles targeted by these assays to include genetic alterations specific to a variety of cancer types, such as KRAS mutations for pancreatic and colorectal cancers or PIK3CA mutations for breast cancer." (PMID 40206799, 2025). "Previous studies have reported that PIK3CA mutation confers resistance in colorectal cancer, lung cancer, and breast cancer." (PMID 41404730, 2025). "This PIK3CA variant represents a known somatic hotspot variant typically found in breast cancer patients (cancerhotspot.org, COSMIC)." (PMID 40260297, 2025). "Over-activation of this pathway occurs in approximately half of luminal-type breast cancers owing to activating mutations in PIK3CA and AKT1 and inactivating alterations in PTEN." (PMID 39466567, 2025). "Within this pathway, PIK3CA is the most frequently mutated gene, identified in nearly 50% of patients with estrogen receptor (ER)‐positive breast cancer." (PMID 40206206, 2025). "It has been approved for treating PIK3CA-mutated, hormone receptor-positive advanced breast cancer and overgrowth syndromes in children over the age of 2 years." (PMID 40492016, 2025). "We previously reported that PIK3CA mutations in serum DNA detected using dPCR for PIK3CA mutations (H1047R, E545K, and E542K) are predictive of recurrence in primary breast cancer." (PMID 40055250, 2025). "In the SOLAR-1 phase II study (NCT03056755), patients with HR+/HER2− advanced breast cancer harboring PIK3CA mutations received alpelisib plus fulvestrant following CD4/6 inhibitor treatment with the aromatase inhibitor." (PMID 40142329, 2025). "Phosphoinositide 3-kinase (PI3K) signaling is hyperactivated in ~70% of breast cancers via mutations in oncogenes including PIK3CA or inactivation/depletion of phosphoinositide (PI)-phosphatases." (PMID 41408399, 2025). "The relationship between PIK3CA mutation and clinicopathological features of breast cancer patients is still controversial." (PMID 40472482, 2025).
breast cancer (continued). "This revealed that 3 to 9% of ER+ breast cancer biopsies with mutations in PIK3CA had co-occurrent alterations in PTEN at the genomic level, with mutations, truncations or homozygous deletions in PTEN." (PMID 40263319, 2025). "Several studies have indicated that PIK3CA mutations activate the PI3K/AKT/mTOR pathway in breast cancer." (PMID 40142329, 2025). "Although PI3K inhibitors have been approved for the treatment of PIK3CA-mutated HR+/HER2- breast cancer, their monotherapy efficacy is limited, and resistance issues exist." (PMID 41280894, 2025). "Alpelisib, a selective inhibitor of the p110α subunit of PI3K, has demonstrated substantial clinical efficacy in hormone receptor (HR)-positive, HER2/erbB2-negative breast cancers harboring PIK3CA mutations." (PMID 41347072, 2025). "Clinical studies on breast cancer have consistently demonstrated a relatively high prevalence of PIK3CA gene mutations among patients with breast cancer." (PMID 40206206, 2025). "PIK3CA mutations were detected at a high frequency in breast cancer and were more commonly found in ERBB2mut than in ERBB2amp tumors (45.0% vs. 35.6%)." (PMID 40178042, 2025). "The phase II BYLieve trial confirmed that adding alpelisib to ET is effective for relapsed HR+/HER2− breast cancer subjects carrying a PIK3CA mutation and progressing on CDK4/6is and ET." (PMID 40244377, 2025). "Analysis of MDSC infiltration in PIK3CA-mutated (PIK3CAMUT) breast cancer tissues from the TCGA BC cohort revealed significant MDSC accumulation in PIK3CAMUT tumors." (PMID 41281644, 2025). "In another experience on breast cancer, postoperative detection of PIK3CA mutations in ctDNA analysis was associated with a high risk of relapse in early stage breast cancer patients." (PMID 40219616, 2025). "Activating PIK3CA mutations, present in up to 40% of hormone receptor-positive (HR+), human epidermal growth factor receptor 2-negative (Her2−) breast cancer (BC) patients, can be effectively targeted with the alpha isoform-specific PI3K inhibitor Alpelisib." (PMID 40113784, 2025). "Upon a genomic analysis, mutations in the PIK3CA gene were detected, which are often associated with endocrine resistance in breast cancer." (PMID 40075655, 2025). "For instance, curcumin, which comes from turmeric, blocks the PI3K/Akt/mTOR signaling pathway frequently activated in breast cancer containing PIK3CA mutations." (PMID 39852145, 2025). "Originally approved for treating PIK3CA-mutated, hormone receptor-positive advanced breast cancer and overgrowth syndromes, alpelisib has also shown efficacy in managing non-islet cell tumor hypoglycemia." (PMID 40492016, 2025). "This variability underscores the importance of considering molecular subtypes when investigating the role of PIK3CA mutations in breast cancer." (PMID 40472482, 2025). "According to The Cancer Genome Atlas (TCGA) dataset, PIK3CA was the most frequently mutated gene in breast cancer occurring in more than 30% of cases, most of which were activating mutations." (PMID 40303291, 2025). "Clinical trials demonstrate the combination of alpelisib with fulvestrant or letrozole in patients with HR-positive, HER2-negative breast cancer with PIK3CA mutation (s) in their tumors." (PMID 41157256, 2025). "Capivasertib (novel inhibitor): Approved in combination with fulvestrant for patients with HR-positive, HER2-negative breast cancer with a PIK3CA/AKT1/PTEN mutation." (PMID 41157256, 2025). "We concluded that autophagy suppression is sufficient for DCA/Metformin hypersensitivity in HR+/Her2− breast cancer with PIK3CA mutations." (PMID 40113784, 2025). "Oncogenic PIK3CA mutations occur in approximately 30 % of human breast cancers, with a higher incidence in HR + cases." (PMID 41281644, 2025).
breast cancer (continued). "A study of cancer genomes with PIK3CA mutations revealed that approximately 15% of breast cancers exhibit multiple PIK3CA mutations, with 95% being double mutations." (PMID 40142329, 2025). "PIK3CA mutations are established oncogenic drivers, with their clinical significance varying across breast cancer subtypes." (PMID 40002579, 2025). "Alpelisib is the only FDA-approved p110α isoform-specific inhibitor, which is in combination with fulvestrant to treat PIK3CA-mutated HR+ HER2− breast cancer up to now." (PMID 39717717, 2025). "Mutations in the oncogene PIK3CA are implicated in many types of solid tumors and are prevalent in estrogen-receptor (ER)-positive Her2-negative (ER+Her2−) breast cancer (BC)." (PMID 40536266, 2025). "Among them, alpelisib is now clinically available to treat hormone receptor-positive/HER2-negative, PIK3CA-mutated breast cancer, whereas inavolisib, more potent than alpelisib in vitro, is under investigation in phase III clinical trials." (PMID 39920872, 2025). "Alpelisib was also tested as monotherapy in heavily pretreated ER + HER2− breast cancer and triple-negative breast cancer with PIK3CA mutations in a phase II clinical trial." (PMID 39717717, 2025). "PIK3CA‐derived mutations were primarily detected in colorectal cancer (11.9%, 7/59), breast cancer (10.9%, 7/64), and gastric cancer (9.7%, 6/62)." (PMID 39748775, 2025). "Our prior study demonstrated that PIK3CA mutations facilitate immune evasion in breast cancer by recruiting myeloid-derived suppressor cells (MDSCs) through activation of the 5-lipoxygenase (5-LOX)-dependent arachidonic acid pathway." (PMID 41281644, 2025). "The next-generation sequencing (NGS) assay revealed a missense mutation within exon 7 in PIK3CA, which is related to the treatment of breast cancer." (PMID 41040523, 2025). "Plasma PIK3CA ctDNA specific mutation detected by next generation sequencing is associated with clinical outcomes in advanced breast cancer." (PMID 40076662, 2025). "The mutation rate of PIK3CA is particularly high in male breast cancer (MBC), ranking first among known BC-associated variations recorded in the COSMIC database." (PMID 39895796, 2025). "The most frequent PIK3CA mutations in primary breast carcinomas were detected in exon 9 (E542K/E545K) (10/14 cases) followed by mutations in exon 20 (3/14 cases) (H1047XR/H1047L) and by mutation in exon 7 (1/14 cases)." (PMID 39929942, 2025). "Breast carcinoma tissue was analyzed by Cobas PIK3CA mutation test for the presence of PIK3CA mutation and immunohistochemistry was applied to assess PD-L1 expression and CD4, CD8, CD68, and CD163 infiltration within tumor." (PMID 41096755, 2025). "Monotherapy of solid neoplasms with PI3K inhibitors proved ineffective, however, several compounds have already been approved for the treatment of PIK3CA-mutated hormone-receptor (HR)-positive/HER2-negative breast cancer (BC) in combination with other agents." (PMID 40507317, 2025). "Mutations in PIK3CA occur in approximately one-third of hormone receptor-positive (HR+)/HER2-negative (HER2−) breast cancer (BC) and represent a target for specific inhibitors." (PMID 40507317, 2025). "PIK3CA mutations are among the most frequent genomic alterations in breast cancer (BC), contributing to disease progression and therapeutic resistance." (PMID 41415546, 2025). "Therapeutics targeting specific driver mutations in PIK3CA have revolutionized the treatment of breast cancer in recent years." (PMID 39711963, 2024). "Use of apelisib or capivasertib for PIK3CA-mutated breast cancer was the third most common target identified by our MTB and all patients had either already received targeted therapy or started this therapy shortly after our recommendation." (PMID 39590164, 2024). "We also studied the association between cyclin D1 and PIK3CA mutations given the established oncogenic role of cyclin D1 in breast cancer, and its deregulation in our experimental system." (PMID 38273040, 2024).
breast cancer (continued). "In the SOLAR-1 trial, treatment with the PI3Kα-specific inhibitor alpelisib in combination with fulvestrant improved outcomes in patients with PIK3CA-mutated ER+ advanced breast cancer." (PMID 38791941, 2024). "Earlier studies showed variable occurrence (25–46%) of PIK3CA mutations in metastatic ER+ breast cancer." (PMID 39596311, 2024). "In Luminal A breast cancer, a primary somatic mutation is found in the PIK3CA gene in approximately 49% of cases." (PMID 38256428, 2024). "For instance, the PIK3CA Q859 and W780 mutations, and AKT E17K/Q79K mutations, confer resistance to inavolisib and alpelisib in breast cancer patients with baseline PIK3CA mutations (H1047R, E542K/E545K)." (PMID 38920692, 2024). "Mutation of the PIK3CA E535 residue, specifically E535A, has been identified a predictive marker in breast cancer." (PMID 38408048, 2024). "Alpelisib plus fulvestrant demonstrated a significant progression-free survival benefit versus fulvestrant in patients with PIK3CA-mutated HR+ /HER2− advanced breast cancer (ABC) (SOLAR-1)." (PMID 39177931, 2024). "Recently, the FDA (Food and Drug Administration) approved testing of breast cancer patients with PIK3CA mutations using tumor tissue and/or circulating tumor DNA isolated from plasma specimens." (PMID 38753638, 2024). "Mutations in the phosphatidylinositol 4,5-bisphosphate 3-kinase catalytic subunit alpha (PIK3CA) gene are highly prevalent (30–40%) in patients with HR+/HER2− advanced breast cancer." (PMID 39742376, 2024). "It has been estimated that about 30% of patients with breast cancer have PIK3CA mutations, followed by PTEN loss due to somatic mutations or epigenetic alterations." (PMID 38672636, 2024). "A previous study on metastatic ER + /HER2- breast cancer showed moderately lower frequencies (35%) of patients having a PIK3CA mutation when assessing with NGS techniques, and out of these 20% had non-hotspot mutations." (PMID 38822093, 2024). "Fortunately, targeted therapy with PIK3CA inhibitors has been shown to clinically benefit in patients with metastatic PIK3CA mutated breast cancer." (PMID 39742376, 2024). "Mutations in PIK3CA are more common in the luminal A subtype of breast cancer and occur at a lower frequency in the triple negative subtype." (PMID 38802751, 2024). "Patients with 6 colorectal cancer (three PIK3CA mutation) and 6 breast cancer (all PIK3CA mutation) were enrolled." (PMID 39070139, 2024). "In breast cancer patients, nearly 35% present with activating mutations in the PIK3CA gene, and 80–90% of these mutations are E542K, E545K, H1047L, and H1047R mutations." (PMID 38257640, 2024). "This inconsistency probably indicates differences in the prognostic and predictive validity or direction of effect of the PIK3CA mutations on different pathohistological subtypes of breast cancer, at different stages, and in relation to different therapies." (PMID 39742376, 2024). "Alpelisib plus fulvestrant displayed an overall response rate (ORR) of 19.0% and median progression-free survival (PFS) around 11 months in PIK3CA-mutated HR+ advanced breast cancer patients progressing on or after treatment with CDK4/6i and/or ET." (PMID 39409880, 2024). "Luminal A breast cancer often harbors PIK3CA mutations, making the PI3K pathway a key target for therapeutic intervention." (PMID 39850811, 2024). "These positive outcomes led to the FDA approval of fulvestrant and alpelisib combination therapy for advanced HR+ breast cancer with PIK3CA mutations." (PMID 38339303, 2024). "The most common mutations of PIK3CA in Taiwanese female breast cancers are in exon 20 (the H1047R mutation), in exon 9 (the E545K mutation), and in exon 9 (the E542K mutation) with frequencies of 41.6%, 18.9%, and 10.3%, respectively." (PMID 38279318, 2024). "Up to 40% of breast cancers with mutations in PIK3CA are estrogen receptor (ER)-positive, contributing to resistance against hormonal therapies." (PMID 39770406, 2024).